LCN15 (lipocalin 15)
Synonyms: UNQ2541; PRO6093
Tractability: Antibody: UniProt places it where antibodies can reach, with high confidence; UniProt predicts a signal peptide or a membrane-spanning region; its Gene Ontology location is reachable by antibodies, with medium confidence.
Gene: Protein-coding gene on chromosome 9 (136,759,634 to 136,766,255, reverse strand). Ensembl gene ENSG00000177984.
Subcellular location: Secreted
Pathways (Reactome):
Transport of small molecules: Transport of fatty acids
Gene Ontology:
Molecular function: protein binding; small molecule binding
Cellular component: extracellular region
Genetic constraint (gnomAD): Loss-of-function variants: 21 observed, 16.43 expected, observed/expected ratio (o/e) 1.28, 90% interval 0.9 to 1.79. The upper end of that interval is the gene's LOEUF score, 1.79, which puts it in group 6 of 6, group 1 being the genes least tolerant of losing a copy. Missense variants: 204 observed, 198.23 expected, observed/expected ratio (o/e) 1.03, 90% interval 0.92 to 1.16. Synonymous variants: 96 observed, 84.02 expected, observed/expected ratio (o/e) 1.14, 90% interval 0.97 to 1.35.
Homologues: Orthologues: chimpanzee LCN15 (97% identical), macaque LCN15 (94% identical), pig LCN15 (71% identical), guinea pig LCN15 (67% identical), dog LCN15 (66% identical). Paralogues in human: PTGDS (30% identical), LCN10 (27% identical), LCN2 (25% identical), LCN6 (23% identical), LCN1 (23% identical), OBP2A (22% identical), OBP2B (22% identical), LCN12 (21% identical), LCNL1 (20% identical), LCN9 (19% identical), LCN8 (16% identical), PAEP (16% identical).
Diseases named in the same sentence as LCN15 in open-access papers:
LCN15 is named in the same sentence as 5 diseases in open-access papers, as found by Europe PMC text mining. Sharing a sentence is not in itself a finding about the gene and the disease. The quoted sentences say what the papers report.
diabetes (1 paper, 2018). "There is very limited information about LCN15 in the literature, and its physiological function is unknown; however, it is a member of the lipocalin gene family, of which LCN2 is a well-studied member involved in obesity and diabetes." (PMID 29736189, 2018).
cancer (2 papers, 2022). A tumor composed of atypical neoplastic, often pleomorphic cells that invade other tissues. "In the 8-mRNA signature (KCNJ18, RPE65, GRIA1, LCN15, C11orf21, ANXA13, FSIP2 and KRT76), the expressions of some mRNAs have been reported to have significant associations with the survival in some cancers." (PMID 35675043, 2022). "As a result, seven DEGs correlated with more than 10 TR-DDR genes (r>0.3) in at least 10 cancers were regarded as candidate genes, including COL2A1 (the R ranged from 0.39 to 0.60), MAGEA4 (0.24–0.62), FCRL4 (0.33–0.62), ZIC1 (0.24–0.33), LCN15 (0.20–0.41), PRSS3 (0.24–0.35), CSAG1 (0.31–0.38)." (PMID 36081518, 2022).
LCN15 also shares sentences with these, for which no sentence is quoted: bacterial infection (1 paper); infection (1); Obesity (1).